IL10 (interleukin 10)
Diseases named in the same sentence as IL10 in open-access papers (continued):
Sharing a sentence is not in itself a finding about the gene and the disease.
tumor (continued). "In a 3D co-culture of non-small cell lung carcinoma cells with CAFs and monocytes, an accumulation of soluble factors (IL-4, IL-10, IL-13, CXCL1) was observed, promoting immune cell infiltration of the tumor and M2-like macrophage polarization." (PMID 35205760, 2022). "M2 macrophages are exposed to IL-4 or IL-13 and produce immunosuppressive substances (IL-10 and TGF-β) that promote tumor growth by increasing STAT3 expression and inhibiting antigen presentation." (PMID 35251014, 2022). "If extrapolated beyond CD4+ T cells, our results on IL-10 signaling supporting the long-term maintenance of immunological memory may help explain recent data showing that IL-10R signaling favors the maintenance of a population of CD8+ T cells that promote tumor control in oncology models." (PMID 35230978, 2022). "For instance, TAM produces anti-inflammatory and growth-promoting cytokines, such as IL-10, IL-6, TGF-β, and prostaglandin E2 (PGE2), to restrict cytotoxic function of T lymphocytes and promote tumor growth." (PMID 36679900, 2022). "As regulated by the primary tumor, MDSCs arrived in the metastatic organs before the tumor cells and conditioned it to promote tumor seeding by secreting b-FGF, IGF-1, IL-10, IL-4, IL-1β, SDF-1, and MCP-1." (PMID 35267547, 2022). "Tumor cells also secrete proteins, such as IL-10 and TGF-β, to remodel the immune microenvironment and promote tumor progression." (PMID 35719915, 2022). "In contrast, factors such as IL-10, TGF-β, and VEGF secreted by M2 macrophages promote tumor progression, angiogenesis, metastasis, and suppression of anti-tumor immunity." (PMID 36120553, 2022). "IL-4 was demonstrated to negatively regulate the anti-tumor function of γδT cells via inhibiting the expression of NKG2D and promoting the IL-10 production from Vδ1 cells, which in turn suppressed IFN-γ production and the proliferation of Vδ2 cells." (PMID 35747139, 2022). "This is associated with the production of immunosuppressive cytokines, such as IL-6, IL-10, and downregulation of MHC I by cancer cells, which reduces the maturation of dendritic cell (DC) and lower Treg recruitment into the tumor microenvironment (TME)." (PMID 36430176, 2022). "At the beginning of tumor genesis, IL-10 might predominantly act as a antitumor factor by potentiating the cytotoxicity of NK cells and CTLs to tumor cells; while with the progression of tumor, IL-10 might mainly act as a potent tumor promoter via the IL-10R expressed on tumor cells." (PMID 36531027, 2022). "TIM-3 expression in Tregs promotes tumor progression and exhaustion of CD8+ T cells enhancing their suppressive activity and IL-10 production." (PMID 36713558, 2022). "In vitro studies revealed that EGFR-targeted CAR-T cells exhibit specific cytolytic activity and produce high levels of cytokine (IL-2, IL-4, IL-10, TNF-α, and interferon-γ [IFN-γ]) against EGFR-positive tumor cells." (PMID 35720364, 2022). "CSCs can recruit immunosuppressive properties of DCs by producing immunosuppressive cytokines, including IL-13, IL-10, IL-4, and co-inhibitory molecules like B7-H3, IDO1 and PD-L1 which induce tumor properties of DCs." (PMID 36207500, 2022). "Other modulators in the TME, such as Tregs, release the cytokines IL-8, IL-10, and TGF-β to downregulate NKG2D ligand membrane expression in HSCs, which suggests tumor progression in HCC patients." (PMID 35757756, 2022). "In TME, IL-10, TGF-β1, VEGF, and other factors secreted by tumor cells or TAMs can inhibit the maturation of DCs, thus avoiding the host's anti-tumor immune response." (PMID 36209263, 2022). "Tregs secrete interleukin-10, -35, and transforming growth factor− (TGF−) in order to suppress the anti-tumor immune response mediated by NK cells, CD4+ T cells, and CD8+ T cells." (PMID 35479081, 2022). "MDSCs also participate in tumor immune tolerance by generating Tregs through the secretion of TGF-β and IL-10." (PMID 35267487, 2022).
tumor (continued). "HCC cell-derived EVs inhibit tumor growth by transferring HCC antigens and antigenic chaperones to DCs, which induces cytolysis and increases IFN-γ expression but decreases IL-10 and TGF-β expression." (PMID 36405712, 2022). "Macrophages secrete various growth factors such as TGF-β, VEGF, PDGF, cytokines such as M-CSF and interleukins, chemokines such as IL-6, IL-10, CCL2, and CXCL, and enzymes such as MMPs which promote tumor growth." (PMID 36679900, 2022). "In contrast, the cytokines IL-10, IL-4 and TGF-β from Th2 cells were proven to promote tumor cell dissemination and metastasis in various cancers." (PMID 35688915, 2022). "Accordingly, immune‐activated M1‐type macrophages (CD11c+CD11b+F4/80+ or CD86+F4/80+CD11b+) were up‐regulated, and a drop in secretion of immunosuppressive cytokines in G6 was observed (which promotes tumor growth, i.e., TGF‐β and IL‐10)." (PMID 36156442, 2022). "To evaluate a prospective immunosuppressive activity of platelets during haematogenous metastasis probably via inducing IL-10, we determined IL-10 levels from PBMC co-cultured with platelet and tumour cell-induced platelet releasates, respectively." (PMID 35285006, 2022). "TAMs, especially the M2 type, can stimulate tumor growth through the secretion of various mediators such as TGF-β, IL-10, and vascular endothelial growth factor (VEGF)." (PMID 36139368, 2022). "M2 macrophages, on the one hand, produce IL-10 and TGF-β, leading to suppression of the general anti-tumor immune response." (PMID 35701829, 2022). "This resulted in overexpression of PD-L1 and IL-10, which limited CD8+ T cell recruitment and promoted tumor formation." (PMID 36300110, 2022). "M2 produces various tumor-promoting factors with the most prominent being vascular endothelial growth factor (VEGF), IL-6, IL-10, and TGF-β." (PMID 35053449, 2022). "In contrast to the effect of celecoxib on tumor lysate induced DCs, we here show that celecoxib reduced TLR-induced production of IL-10, IL-12, TNF-α, and IL-6." (PMID 36227963, 2022). "During the GBM process, hyperactivity of HDAC3, 5, and 9 is expressed in IL-4-induced M2 GAMs that increase the levels of TGFβ and IL-10, resulting in exacerbating the immunosuppressive capacity of GBM tumor cells." (PMID 35572545, 2022). "One, PAF-induced release of inflammatory cytokines, such as IL-10, Treg, IL-1, and TNF-alpha lead to systemic immunosuppression and tumor metastasis." (PMID 35603177, 2022). "Th2 is one of the special subtypes of CD4+ helper T cell (Th cell) that mainly secretes cytokines such as IL-4, IL-5, and IL-10, and excessive Th2 cells could affect the tumour-suppressive immune microenvironment, seriously reducing the anti-tumour effect, leading to the malignant growth of tumours." (PMID 35591854, 2022). "Mechanistically, MARCO+ macrophages enhance the proliferative activity of Tregs and IL-10 production as well as reduce CD8+ T cell activity, creating a suppressive microenvironment suitable for tumor cell survival." (PMID 36510315, 2022). "Tumor cells also release many cytokines including CCL2, CXCL12 and CSF1 that attract TAMs to help tumor escape by producing IL-10 and also directly inhibiting CAR T-cells via PD-1-PD-L1 interaction." (PMID 36569859, 2022). "M2 macrophages directly inhibit CD4+ T cell-mediated tumor killing through cell-cell contact or release TGF-β and IL-10 and accelerate lymphatic tumor metastasis." (PMID 36072667, 2022). "LAG3 is expressed on regulatory T cells in tumors and induces the production of IL-10 and TGF-β1, which helps tumor immune escape." (PMID 35279104, 2022). "On the one hand, Tregs can release immunosuppressive cytokines, such as IL-35, IL-10, and transforming growth factor β (TGF-β), which inhibit the function of CD8+ T cells and promote tumor cell growth." (PMID 36532066, 2022).
tumor (continued). "The blockade of the constitutive expression of STAT3 in tumor reduced the expression of VEGF, IL-6, and IL-10, which neutralized the inhibitory effect of dendritic cell maturation." (PMID 35936759, 2022). "The upregulated expression of IL-23 activates Treg proliferation and promotes IL-10 and TGF-β expression, resulting in the suppression of tumor cell killing by cytotoxic lymphocytes." (PMID 36233088, 2022). "Several tumor-derived cytokines such as TGF-β, TNF, IL-6 or IL-10 are able to prevent the maturation of DCs, the infiltration of mature DCs, the presentation of antigens and the activation of T and NK cells." (PMID 36611932, 2022). "Compared to PANC1 and BxPC3 tumor, coro1a: GFP+ cells from AsPC1 xenografts expressed a low level of TNF-α and IL-12, and a higher level of IL-10." (PMID 35742884, 2022). "γδTreg cells were found to impair DC maturation and function and CD8+T cell-mediated anti-tumor function in cancer patients via TGF-β, IL-6 or IL-10 dependent or independent manner." (PMID 35747139, 2022). "The mRNA levels of INOS, TNF-α, IRF5, IL-10, TGM2, and Arg-1 in the blood of tumor-bearing mice treated with the exosomes were detected by qRT-PCR." (PMID 35600340, 2022). "As in other tumor types, a pro-tumoral cytokine network induced by CD4+ T and myeloid-lineage cells in the TME, including prostaglandin E2 (PGE-2), IL-6, IL-10, and TGF-β, exacerbates the repression of effector CD8+ T cell response and induces Tregs." (PMID 35920986, 2022). "IL-10 production from B cells impairs inflammatory cytokines, including TNF-α and IFN-γ, secretion from cytotoxic T cells to promote tumor growth." (PMID 36033455, 2022). "IL-10 suppresses the multiplication of T lymphocytes, downregulates MHC Class II, and promotes the development of tumor evolution." (PMID 35054779, 2022). "They produce several factors regulating inflammation and tissue homeostasis that allow for tumor growth and metastasis, such as TGFβ, VEGF, IL-10, and reactive oxygen species (ROS)." (PMID 36310582, 2022). "Previous studies have demonstrated that multiple immunosuppressive cytokines, such as IL-6, IL-10 and TGF-β promote the maturation and recruitment of immunosuppressive cells and impair the anti-tumor functions of NK cells and CD8+ T cells." (PMID 35656301, 2022). "M2 macrophages promote and produce high levels of cytokines that stimulate tumor growth and progression via the production of anti-inflammatory stimuli such as TGF-β1 and IL-10." (PMID 35740547, 2022). "On the other hand, IL-10 promotes the proliferation of CD8+ T cells and its cytotoxicity to tumor cells." (PMID 36531027, 2022). "Galectin-1 stimulates IL-6, and IL-10 secretion in PDAC activates CAF expression and promotes stromal fibrosis of the tumor." (PMID 36428567, 2022). "The plasma concentrations of IL-6, IL-10, and TNF-α were significantly increased in the serum of tumour-bearing SID animals compared to the healthy controls." (PMID 36010845, 2022). "Conventionally, reactive oxygen species (ROS)-producing M1 macrophages are regarded as inhibitors of tumor growth, whereas IL-10 and TGF-β producing M2 macrophages are thought to promote tumor growth." (PMID 35326515, 2022). "In the study of MC38 colon cancer cell line inoculation in vivo, which is reported that B cells suppress anti-tumor T cell responses in this cell line, and B cells secreted GABA promotes tumor growth by facilitating IL-10 production from macrophages." (PMID 36033455, 2022). "Cancer cells produce IL-10, CCL2, and VEGF that induce M2 macrophage polarization, promoting tumor immune evasion." (PMID 36555392, 2022). "For example, once antigens on the surface of tumor cells are recognized, the tumor cells start to overexpress suppressive cytokines, such as IL6, IL10 or TGF-β, which can block the immune system." (PMID 35624717, 2022).
tumor (continued). "Molecular characterization of the tumor debris resulting from the two types of HIFU showed that only M-HIFU uniquely induced a fragmented RNA, DNA and protein profile in tumor debris, reducing the presence of immunosuppressive factors TGF-β and IL-10." (PMID 36569907, 2022). "Bregs highly express and produce immunosuppressive and tumor-promotive molecules, such as PDL1, IL10, and TGFβ, as reviewed elsewhere." (PMID 36211375, 2022). "IL-10 has complex effects on the regulation of different components of the immune system, meaning, for example, that the immune control of other infections, tumor development, or graft versus a host disease in transplant recipients could potentially be influenced." (PMID 36445084, 2022). "CDH17 ‘high-methylation’ cases, showed increased expression of IL12B, IL10, CXCL9 and 10 and CCL2 compared to CDH17 ‘low-methylation’ cases, suggestive of a favourable cytokine/chemokine ‘milieu’ in these tumours." (PMID 36612154, 2022). "Tumour cells, and some TME resident immune cells, also secrete exosomes that mediate the generation of IL-10 producing and PD-1-expressing Bregs." (PMID 35350071, 2022). "We further studied the expression of suppressive function-related genes in MDSCs, and the IL-10, IL-6, and TGF-β signaling pathways were upregulated after cryo-thermal therapy compared with those in tumor-bearing control." (PMID 36389684, 2022). "Despite a greater proportion of M1 macrophages in the TME, M2 macrophages expressed higher gene level of CD163, MRC1 (CD206), TGF-β, IL10, VEGFA, and MMP9, which exhibited stronger tumor-promoting ability." (PMID 35033156, 2022). "In summary, CSCs release a variety of immunosuppressive cytokines and chemotactic factors such as; PGE2, IL-10, TGF-β, IL-4, IL-13 and IL-35 that affect different immune cells in the TME and promote tumor invasion and progression." (PMID 36207500, 2022). "GBM tumor cells also foster pericytes and endothelial cells to produce more IL-10 and TGFβ by activating the IL-6/STAT3 signaling pathway, thus inciting tumor growth." (PMID 35572545, 2022). "TANs also play a role in tumor invasion and angiogenesis in primary and metastatic sites by generating MMP9, VEGF, HGF, PAF, IL-10." (PMID 36419156, 2022). "M2 polarizing factors are hypoxia and acidity of the tumour microenvironment, IL4, TGFB and IL10 and CSF2." (PMID 35445563, 2022). "M1 macrophages (CD86+ and CD80+) release pro-inflammatory cytokines (e.g., IL-6, IL-12, TNF-α) to play an anti-tumor role, while M2 macrophages (CD206+) release pro-tumor cytokines (e.g., IL-4, IL-10, IL-13) to promote tumor progression and metastasis." (PMID 35432300, 2022). "Cytokines secreted by Tregs, such as IL-10, IL-35, and TGF-β, are key factors in inhibiting the function of NK cells and effector T cells and promoting tumor progression." (PMID 36246629, 2022). "Tumour-derived TGF-β, IL-10, and vascular endothelial growth factor (VEGF) promote the expansion of natural Treg (nTreg) cells assisted by antigen-presenting cells (APCs) in a tolerogenic manner." (PMID 36569832, 2022). "To prove that the suppression of tumor control is also mediated by IL-10, we performed an FBL-3 tumor control experiment in which we treated mice with an IL-10 blocking antibody, starting on the day of F-MuLV Env (SU+TM) immunization." (PMID 36605206, 2022). "Cancer cells suppress NK cell function through expression of TGF-β, IL-10, indoleamine 2,3-dioxygenase (IDO), and matrix metalloproteinases (MMPs), which impair NK cell tumor recognition and killing via the downregulation of cytotoxicity receptors." (PMID 36077755, 2022). "Neospora caninum treatment significantly increased the mRNA expression levels of IL-12, IFN-γ, IL-2, IL-10, TNF-α, and PD-L1 in the TME, and IL-12 and IFN-γ in the spleen of tumor-bearing mice (P < 0.05)." (PMID 36138417, 2022).
tumor (continued). "TAMs exhibit either an immunosuppressive M2-like phenotype, increasing production of anti-inflammatory factors IL-10 and TGF-β, or an anti-tumor M1-like phenotype, releasing pro-inflammatory cytokines IL-12, IL-1, IL-6, and TNF-α." (PMID 35236203, 2022). "Tumor cells secrete immunosuppressive cytokines (e.g., TGF-b, IL-10, VEGF), drive expression of inhibitory receptors and ligands (e.g., PD-L1/2, CTLA-4) and reduce tumor-specific MHC-I antigens." (PMID 36010965, 2022). "This links lytic EBV expression to conditioning of the tumor microenvironment, as TNF is involved in inflammation and immune regulation, CCL5 is important in the recruitment of myeloid suppressor cells and IL10 suppresses T cell responses." (PMID 36560713, 2022). "Tumour-secreted miR-214 mobilises Tregs to release higher levels of IL-10 by downregulating PTEN, leading to immune-suppression and rapid tumour growth." (PMID 36613640, 2022). "Tregs secrete pro-tumorigenic, Th2-polarizing cytokines such as interleukin (IL)-10 and transforming growth factor (TGF)-β, which induce immune suppression and hinder the anti-tumour activity of T cells." (PMID 35454848, 2022). "Compared to B-MF, FOB upregulated numbers of CD4+ T cells but decreased frequency of IL10+ CD4+ T cells and GrB+ and Lamp1+ (cytolytic) CD8+ T cells in the tumor, implying that the two cells support cancer independently and without reversal of B-MF to B cells." (PMID 36104343, 2022). "After binding to 4-1BB on tumor cells, NK cells had an increased CD73 surface expression, which triggered STAT3 activation and TGF-β/IL-10 secretion correlating with reduced CD4+ T cells proliferation and IFNγ production." (PMID 35769460, 2022). "Tumor-infiltrating Bregs in GC consist of three phenotypes: CD19+CD24hiCD38hi transitional cells, CD19+CD24hiCD27+ memory cells, and IL-10 producing CD27+CD10- cells." (PMID 36618354, 2022). "Through transduction of IL10-induced signaling, IL10RB (IL10 receptor subunit beta) contributes to the immunosuppressive tumor microenvironment." (PMID 35681785, 2022). "On the other hand, in solid tumours, IL-10 production by components of the TME (such as TAMs) can, among others, contribute to downregulate CD103+cDC1 tumour-infiltrating DCs-derived IL-12 production." (PMID 35406451, 2022). "Rituximab-mediated downregulation of IL10 suppresses BCL2 expression and enhances apoptosis in tumour cells." (PMID 36090032, 2022). "Tregs release inhibitory cytokines (such as IL-10 and TGF-β) to prevent the infiltration and activity of tumor-specific T cells." (PMID 36439457, 2022). "TAMs secrete cytokines (IL6, IL10, etc.)and exosomes (miR-21-5p, miR-155-5p, etc.)through NFKB1 signaling pathway, STAT3 signaling pathway, and other pathways to act on tumor cells and immune cells, regulating the process of CRC." (PMID 35186730, 2022). "Compared with the normal tissues, FN1, IL10, and MYC were highly expressed, while the expression of CD247 was decreased in tumor bladder tissues." (PMID 36389789, 2022). "Tregs infiltration directly inhibits cytotoxic T cells proliferation and produces immunosuppressive cytokines such as IL-10, IL-35 and transforming growth factor β (TGF-β), thereby supporting tumor immune escape and potentiating tumor progression." (PMID 35843942, 2022). "For instance, several soluble substances released in the TME, including IL-6, IL-10, IDO, M-CSF, transforming growth factor-β1 (TGF-β1), PGE2, and VEGF, can assist the immunosuppression of tumor-infiltrating DCs." (PMID 36703982, 2022). "The IL‐12/IL‐10 ratio significantly increased upon 3p‐125b‐ASO‐loaded RBCEV treatment, suggesting a pro‐inflammatory tumour microenvironment." (PMID 35430766, 2022). "In the progress of tumor immune response, Tregs differentiated from ordinary T cells can secrete TGF-β, IL-10, and IL-35, which suppress antitumor immunity and promote the formation and progression of tumors." (PMID 35493077, 2022).